PKD2 (polycystin 2, transient receptor potential cation channel)
Diseases named in the same sentence as PKD2 in open-access papers (continued):
Sharing a sentence is not in itself a finding about the gene and the disease.
cyst (continued). "Disease causing mutations in Polycystin-1 (PKD1; ~85% of cases) and Polycystin-2 (PKD2; ~15% of cases) are known, but the complex mechanisms for cyst development and cyst growth are still poorly understood." (PMID 32859916, 2020). "The genetic mechanisms that are known focus on mutations in the genetic drivers polycystin-1 (PKD1) and polycystin-2 (PKD2) that result in cyst formation once a certain threshold of insufficient protein product is reached." (PMID 33022986, 2020). "Nevertheless, we have previously shown that genetic knockout of miR-17~92 or pharmaceutical inhibition of miR-17 both reduce cyst burden in an orthologous Pkd2-KO mouse model." (PMID 30760828, 2019). "Densitometric analysis revealed that non-cyst-forming Pkd2+/− embryonic kidneys express approximately half the protein level of Wt kidneys (average = 56.04 ( ± 19.68)% of Wt levels)." (PMID 31492868, 2019). "We recently used this approach to identify several CFTR enhancers and applied it here to a large region spanning the PKD2 locus in primary human cyst renal epithelial cells." (PMID 29986647, 2018). "Clinically identified pathogenic mutations in either PKD1 or PKD2 were thought to result in abnormal PKD1/PKD2 channel function and dysregulated cilium signaling, ultimately initiating cyst formation." (PMID 29899465, 2018). "We assumed that the regulatory elements controlling PKD2 in this cell line should be, at least in part, similar to the regulatory network in cyst epithelial cells." (PMID 29986647, 2018). "We confirmed cyst progression upon reduction of Pkd1 or Pkd2 in adult renal collecting duct epithelia." (PMID 29443690, 2018). "To explore the mechanisms by which metformin inhibits cyst growth, we analysed the effect of metformin on leukocyte infiltration in the pkd2 morphants." (PMID 28769124, 2017). "In the current study, we demonstrated that metformin activated the phosphorylation of AMPK and prevented cyst formation in a zebrafish pkd2 model." (PMID 28769124, 2017). "In this study, we used a zebrafish model of PKD2 for evaluating the effects of metformin on cyst initiation." (PMID 28769124, 2017). "Chemical compound screening in zebrafish pkd2 models indicated that histone deacetylase inhibitors inhibited cyst growth." (PMID 28769124, 2017). "Metformin treatment resulted in a significant reduction (42% to 61%) of cyst formation in the Tg(wt1b:GFP) pkd2 morphants compared with untreated controls at 48 hpf (P < 0.01)." (PMID 28769124, 2017). "In accordance with this study, we found that metformin inhibited early cystogenesis in zebrafish pkd2 morphant embryos, indicating that metformin can inhibit cyst growth in both PKD1 and PKD2 animal models." (PMID 28769124, 2017). "Knockdown of either Pkd1 or Pkd2 in mIMCD cells resulted in remarkable defects of F-actin structure and accelerated cyst growth in 3D culture." (PMID 29074972, 2017). "Stimulation of polarized epithelial monolayers with fluid flow induced phosphorylation and nuclear export of HDAC5 whereas dwonregulation of HDAC5 or treatment with TSA reduced cyst formation in Pkd2−/− mouse embryos." (PMID 25972812, 2015). "Knockout of the polycystic kidney disease genes PKD1 or PKD2 induces cyst formation from kidney tubules." (PMID 26493500, 2015). "The relevance of the KV as a model for ADPKD cyst inflation is highlighted by the fact that pkd2-morphants have significantly larger KVs than WT siblings." (PMID 26432887, 2015). "PKD2 morphants demonstrate increased ERK activation in primary cilia, which is linked to enhanced cell proliferation and fluid secretion and hence cyst enlargement in PKD." (PMID 24098285, 2013). "For example, TNF-αwas reported to trigger cyst formation in both wild-type and Pkd2+/− kidney organ cultures, suggesting a role for inflammatory pathways in cyst growth." (PMID 23209428, 2012).
cyst (continued). "Deregulation of PKD1 or PKD2-coding polycystin protein level results in initiation of cyst formation, followed by several signaling pathways that mediate cyst growth and expansion." (PMID 22347511, 2012). "In a recent study, it was shown that the inflammatory cytokine, TNF-α, negatively modulates the function of PC2 and promotes cyst formation in Pkd2+/- mice." (PMID 20587063, 2010). "The Han:SPRD-Cy rat, although lacking a defined mutation in Pkd1 or Pkd2, exhibits slowly progressive cyst formation and has been used extensively in long-term pharmacological and dietary intervention studies." (PMID 40801635, 2025). "PKD2-/- organoids rapidly formed spontaneous cysts, and the efficacy of drugs targeting the epigenome was demonstrated, confirming the role of epigenetic dysregulation in cyst progression." (PMID 40722835, 2025). "We previously showed a reduction in cyst progression in BB‐FCF‐treated pkd2 knockdown zebrafish." (PMID 38561249, 2024). "This suggests that the acute derepression of Pkd1/Pkd2 may prevent disease onset or even halt cyst growth in established PKD." (PMID 39595570, 2024). "Therefore, we compared our data to models differing in Cre expression, target gene (Pkd2 vs. Pkd1), age and method of induction, age at sacrifice, cyst burden at time of collection, and number of mice used for analysis." (PMID 39666736, 2024). "Importantly, the pannexin‐1 inhibitor BB‐FCF reduced cyst progression and increased survival in a pkd2 zebrafish model of ADPKD." (PMID 38561249, 2024). "We opted for a model with systemic Pkd2 deletion and cyst initiation in young, developing kidneys." (PMID 39666736, 2024). "Reducing renal macrophages using Cx3cr1-deficient mice attenuated cyst severity in adult-induced Pkd2 mutants in the absence of injury." (PMID 36457161, 2023). "However, cyst growth rate over time is the same in Pkd1 and Pkd2 patient populations, suggesting that the difference in disease progression is due to cyst initiation." (PMID 35253003, 2022). "A third study showed that knockdown of either AC5 or AC6 attenuated the increase in cAMP levels in PC2 deficient renal epithelial cells and that AC5/Pkd2 double mutant mice had less kidney enlargement, lower cyst index, and improved kidney function compared to Pkd2 mutant mice." (PMID 36120538, 2022). "Among those cytokines, TNF-α, which is present in the cystic fluid of human ADPKD kidneys, can disrupt the localization of polycystin-2 to the plasma membrane and primary cilia through a TNF-α induced scaffold protein FIP2, to promote cyst formation in organ cultures and in Pkd2 mutant mice." (PMID 35847973, 2022). "The inhibition of mitochondrial function by anti-miR~17-92 attenuates disease progression in ADPKD mouse models irrespective of the mutated gene (Pkd1 or Pkd2), the type of mutation (null or hypomorphic) or the dynamics of cyst growth." (PMID 34901057, 2021). "Cyst formation was visualized under a microscope (5×) in both groups; however, the percentage of cyst formation in the Pkd2 morphants significantly decreased after treatment with 10 μM NS398 (46.9% in DMSO‐treated morphants vs 23.4% in NS398‐treated morphants, p < 0.05)." (PMID 34551202, 2021). "Our finding that the loss of Pkd2 activates JNK signaling could indicate that JNK activation drives cyst formation, or cyst formation could activate JNK signaling." (PMID 34962918, 2021). "In addition to driving cyst progression in juvenile Pkd2 mutant kidneys, JNK signaling also contributes to cyst progression in adult Pkd2 mutant livers." (PMID 34962918, 2021). "Mechanisms of cyst expansion in ADPKD and the associated increase in TKV are based on reduced intracellular Ca2+ influx caused by mutations in either PKD1 or PKD2, increased cellular adenosine 3′, 5′-cyclic monophosphate (cAMP) levels, and aberrant Ras/Raf/ERK activation." (PMID 33471240, 2021).
cyst (continued). "Pkd2+/- mice develop larger, more pronounced kidney cysts when treated with Tumor Necrosis Factor alpha (TNFα, an inflammatory cytokine) to induce stress as compared to wild-type littermates, whereas treatment of Pkd2+/- mice with TNFα inhibitor blocked cyst formation." (PMID 31941974, 2020). "Fenofibrate treatment increased Pparα expression in Pkd2-KO kidneys, whereas it reduced kidney-weight-to-body-weight ratio, cyst index, and proliferation suggesting that increasing Pparα expression attenuates cyst growth." (PMID 28205547, 2017). "In accordance with these findings, we observed that metformin reduced the recruitment of macrophages in pkd2 morphants, which could be an alternative mechanism through which metformin reduces cell proliferation and cyst formation." (PMID 28769124, 2017). "miR-17 expression was increased in cyst epithelia of both Pkd1-mutant and Pkd2-KO kidneys." (PMID 28205547, 2017). "In ADPKD kidneys, somatic inactivation of PKD1 or PKD2 is a critical step in cyst formation." (PMID 28168444, 2017). "Thus, deletion of miR-17∼92 inhibited cyst proliferation and disease progression in both Pkd1-KO and Pkd2-KO models." (PMID 28205547, 2017). "Furthermore, it was demonstrated that cystic kidney phenotypes were reduced in Hdac5, Pkd2 double null mouse embryos, and that TSA administration decreased cyst formation in Pkd2 mutant embryos." (PMID 23052657, 2013). "In Pkd2-deficient models, loss of Wnt-induced Ca+2 signaling and defects in cell migration were observed, underscoring the importance of non-canonical Wnt signaling in preventing cyst formation." (PMID 40801635, 2025). "ADPKD is usually caused by mutations in the PKD1, PKD2, or GANAB genes which encode polycystin 1 (PC1) and polycystin 2 (PC2), respectively, and leads to excessive proliferation of the renal tubular epithelium, causing cyst formation and progressive renal interstitial fibrosis (RIF)." (PMID 35205236, 2022). "However, deletion of miR-214 in Pkd1 or Pkd2 mouse model aggravates the cyst growth." (PMID 33809516, 2021). "The lack of a second mutation in either PKD1 or PKD2 prompted us to test for the presence of other somatic mutations that might explain cyst formation." (PMID 32163234, 2020). "For proof of principle, we used tubuloids generated from an inducible Pkd2 knockout system (Pkd2fl/fl Pax8rtTA TetOCre +mTmG), demonstrating the ability to track the morphological, protein, and genetic changes that correlate with observable and quantifiable cyst formation." (PMID 32513820, 2020). "Of the four ADPKD patients with no mutation detected in PKD1, PKD2, or any cyst-pathway gene, two were at CKD stage 5 but had small atrophic kidneys (P2 and P9), one was at stage 3 with typical ADPKD features (P4), and one had very mild disease with CKD stage 1 at age 74 (P8)." (PMID 31488014, 2019). "Conditional repression of either Pkd1 (Pax8rtTA; TetO-cre; Pkd1fl/fl) or Pkd2 (Pax8rtTA; TetO-cre; Pkd2fl/fl) results in kidney cysts within 10 weeks after the start of doxycycline induction, suggesting that expression of both genes is necessary to prohibit cyst development in mature mice." (PMID 29443690, 2018). "However, our results do not exclude a role for PI3K in PKD patients, where cyst growth is driven by mutations in the PKD1 or PKD2 gene." (PMID 28644734, 2017). "Since cyst-lining cells lose expression for Nek1, we suggest that stochastic inactivation of Nek1 is required for the manifestation of the PKD phenotype, as it is in humans and animals with heterozygous germ line mutations in PKD1 or PKD2 to manifest autosomal dominant PKD." (PMID 25030234, 2014). "Similarly, data from mice with mutations in polycystic kidney disease genes Pkd1, Pkd2, and Pkhd1 are conflicting and suggest that loss of oriented cell division alone does not initiate cyst formation." (PMID 23351924, 2012).
cyst (continued). "Small organoids containing 1–2 nephrons were generated on microwell patterned plates, enabling spontaneous cyst formation in PKD1-/- and PKD2-/- organoids." (PMID 40722835, 2025). "These phenomena were also manifested in PKD1 (RC/RC) and PKD2 (WS25/−) mice, with MRTF translocation and overexpression occurring predominantly in dilated tubules and the cyst-lining epithelium, respectively." (PMID 38891116, 2024). "In ADPKD, after knockdown of Pkd1 or Pkd2, C-C motif chemokine ligand 2 (CCL2) was highly upregulated at the onset of cyst formation." (PMID 37583898, 2023). "We next investigated the rate of cyst progression and the number of CD206+ R2 macrophages in adult-induced Pkd2 mutant mice." (PMID 36457161, 2023). "The other ADPKD gene, PKD2, also contains a 3′-UTR miR-17 binding motif; remarkably, deleting this miR-17 motif increases Polycystin-2 (PC2) levels and attenuates cyst growth in Pkd1-mutant models." (PMID 35965273, 2022). "However, TMEM33 does not exhibit any significant effect on protecting against or rescuing cystic disorders in zebrafish (tail curling and pronephric cyst formation) caused by PKD2 deficiency, suggesting that ER-localized PKD2 may not be relevant to ADPKD." (PMID 36035467, 2022). "Remarkably, Pkd2 is also inhibited via its 3′-UTR miR-17 motif, and Pkd2∆17-induced Polycystin-2 derepression retards cyst growth in Pkd1-mutant models." (PMID 35965273, 2022). "This cluster was stated to modulate the cystic growth in the kidney by triggering cyst epithelial proliferation and inhibiting the post-transcriptional expression of PKD1, PKD2, and hepatocyte nuclear factor 1β (HNF-1β)." (PMID 35205236, 2022). "Both miR-214 and DNM3OS are upregulated in cystic kidneys from Pkd1 and Pkd2 mouse models, and human ADPKD, specifically in interstitial cells in the cyst microenvironment." (PMID 33809516, 2021). "Particularly, miR-214 is upregulated in both mice and human PKD, while miR-214 deletion worsened cyst enlargement in the Pkd2 KO murine model of ADPKD and increased cyst-related inflammation." (PMID 34901057, 2021). "ADPKD is caused by mutations in the PKD1 and PKD2 genes, coding for polycystin-1 (PC1) and polycystin-2 (PC2), respectively, resulting in cilia alterations and cyst formation." (PMID 34339420, 2021). "An integrated analysis of miRNA and RNA-sequencing was employed in to investigate the miRNA profiles correlated with the severity of cyst development in two ADPKD models, kidney-specific Pkd1 or Pkd2 KO mice, at three time points, P1, P3, and P7." (PMID 34901057, 2021). "They induced a PKD1 or PKD2 knock-out in hESC cells using the CRISPR/Cas9 technology and observed tubular cyst formation in derived kidney organoids." (PMID 32630605, 2020). "Mutations of one or more PKD genes, including PKD1 (in 78% of disease pedigrees), PKD2 (in 13% of disease pedigrees) and GANAB (in ~0.3% of disease pedigrees) result in cyst formation." (PMID 32724471, 2020). "However, the relevance of this finding to ADPKD is unclear because whether miR-17 can modulate cyst growth when Pkd1 or Pkd2 are already mutated has not been studied." (PMID 28205547, 2017). "Recent data yielded from the zebrafish model of ADPKD where PKD2 is knocked-down, described increased P2X7R mRNA expression at an early stage, which coincided with cyst formation in the glomerulus and tubular regions in 75% of PKD2 morphants." (PMID 24098285, 2013). "While kidney injury is known to accelerate cyst formation, unilateral ureteral obstruction did not alter Pkd2-c-Halo expression or distribution." (PMID 41665947, 2026). "Organoids generated from CRISPR-edited iPSCs harboring mutations in PKD1 or PKD2, as well as those derived from ADPKD patient samples, can spontaneously form cyst-like structures without the need for exogenous manipulation." (PMID 40801635, 2025).
cyst (continued). "Genetic tests are frequently negative for PKD1/PKD2, and total cyst volume and residual tissue volume do not increase the prognostic value of MRI in patients with these radiological characteristics." (PMID 39928271, 2025). "Notably, about 10% of patients with atypical or “class 2” cyst distributions, described as unilateral, segmental, asymmetric, lopsided, or with atrophy, were excluded from the Mayo Clinic classification, but have a mild prognosis and are less likely to have a pathogenic PKD1 or PKD2 variant." (PMID 38707833, 2024). "Pathogenic variants in DNAJB11 are associated with cyst formation without kidney enlargement, but in contrast to ADPKD due to PKD1 or PKD2 mutations, also demonstrate chronic interstitial fibrosis." (PMID 38707833, 2024). "We found that ALG9 was present in the cyst wall lining of both ADPLD patients but absent from the cystic wall lining of the ADPKD patient with the PKD2 (c.2584del) variant." (PMID 37761895, 2023). "With this model, we observed that mutation of Cx3cr1 resulted in significant reduction in the number of CD206+ R2 and led to markedly attenuated cyst severity in Pkd2 mutant kidney in the absence of Cx3cr1." (PMID 36457161, 2023). "Thus, we crossed Cx3cr1 null mice (Cx3cr1GFP/GFP) to the Pkd2 conditional mutants (Cre+Pkd2) to prevent the accumulation of resident macrophages, including the CD206+ subtype, and evaluated the impact on cyst formation in the adult-induced mutant kidneys." (PMID 36457161, 2023). "More importantly, analysis of renal histology, cystic index, 2KW/BW and blood urea nitrogen (BUN) indicated that the cyst progression was attenuated, and renal function was improved, in Pkd2 mutant kidneys in the absence of Cx3cr1." (PMID 36457161, 2023). "ALG9 expression was absent in cyst wall lining from ALG9- and PRKCSH-caused ADPLD patients but present in the liver cyst lining derived from an ADPKD patient with a PKD2 variant." (PMID 37761895, 2023). "The authors also found that BB‐FCF, a nonselective pannexin‐1 inhibitor, reduced cyst development in pkd2 zebrafish morphants." (PMID 37024297, 2023). "In this study, we find that — prior to cyst formation — flow-dependent transport is absent in PT from Pkd2–/– mice and that flow dependence can be restored by a dopamine antagonist." (PMID 33886508, 2021). "Interestingly, cyst growth and cystic index (ratio of cyst volume to TKV) varies significantly between the PKD1 and PKD2 genotypes, as patients within the PKD1 population tend to develop cysts earlier." (PMID 32940759, 2021). "Perhaps ectopic Shh expression in non-dilated tubules has not been appreciated in other models (e.g. homozygous Pkd1 or Pkd2 mutants) due to early and rapid cyst progression making it difficult to assess non-dilated tubules." (PMID 27853247, 2016). "MRI imaging data from the CRISP study suggests that this is due to a lower number of cysts being present in PKD2-related disease, rather than differences in the rate of cyst growth or renal enlargement." (PMID 22863349, 2012). "The requirement of a minimum of 8 years follow-up imaging may have led to a bias toward having more PKD2 patients since some PKD1 patients reached endpoints excluding their participation before 8 years had elapsed such as end-stage kidney disease, cyst aspirations, and tolvaptan therapy." (PMID 38877066, 2024). "Moreover, the pkd2 zebrafish model also reflects a more rapid progression of ADPKD, as 5 days postfertilization almost 80% of the pkd2 knockdown zebrafish in the vehicle group had already died and exhibited a large cyst in the pronephros." (PMID 38561249, 2024). "Importantly, BB‐FCF treatment did also not reduce the formation of cysts in the pkd2 zebrafish model, but instead mainly slowed cyst growth." (PMID 38561249, 2024).